ZNF836 (zinc finger protein 836)
Description:
May be involved in transcriptional regulation.
Synonyms: FLJ16287
Tractability: PROTAC: ubiquitination databases record sites on it.
Gene: Protein-coding gene on chromosome 19 (52,153,864 to 52,171,643, reverse strand). Ensembl gene ENSG00000196267.
Subcellular location: Nucleus
Gene Ontology:
Molecular function: transcription cis-regulatory region binding
Biological process: negative regulation of transcription by RNA polymerase II; regulation of DNA-templated transcription
Cellular component: nucleus; cytoplasm
Genetic constraint (gnomAD): Loss-of-function variants: 7 observed, 5.71 expected, observed/expected ratio (o/e) 1.23, 90% interval 0.68 to 1.88. That is too few expected variants to judge how well the gene tolerates losing a copy. Missense variants: 994 observed, 1,170 expected, observed/expected ratio (o/e) 0.85, 90% interval 0.81 to 0.89. Synonymous variants: 363 observed, 402.32 expected, observed/expected ratio (o/e) 0.9, 90% interval 0.83 to 0.98.
Homologues: Orthologues: chimpanzee ZNF836 (99% identical), macaque ZNF836 (97% identical). Paralogues in human: ZNF841 (75% identical), ZNF546 (37% identical), ZNF616 (37% identical), ZNF267 (34% identical), ZNF528 (33% identical), ZNF28 (32% identical), ZNF534 (31% identical), ZNF540 (31% identical), ZNF571 (31% identical), ZNF573 (31% identical), ZNF658 (31% identical), ZNF33B (31% identical), and 164 more.